BRCA1 (BRCA1 DNA repair associated)
Diseases named in the same sentence as BRCA1 in open-access papers (continued):
Sharing a sentence is not in itself a finding about the gene and the disease.
breast cancer (continued). "A retrospective, multicenter cohort study was performed from 1996 to 2011 and comprised 6,235 women with unilateral breast cancer from 6,230 high risk families that had tested positive for BRCA1 (n = 1,154) or BRCA2 (n = 575) mutations or tested negative (n = 4,501)." (PMID 23216834, 2012). "The clinical role of BRCA1 and BRCA2 mutation testing for younger women with breast cancer is in rapid transition because of advances in gene sequencing technologies and accumulating evidence for the contribution of BRCA mutation status to acute management of early breast cancer." (PMID 22838957, 2012). "As the majority of BRCA1 cancers are ER-, there is also recent evidence suggesting that E3 ubiquitin-ligases (related family of RNF146, a candidate gene in 6q22.33) and BRCA1 may act in conjunction to regulate ER-mediated pathways in breast cancer tumorigenesis." (PMID 22768030, 2012). "In the present study, we investigated the germline CNV profiles of 68 unrelated familial and early-onset breast cancer patients who were negative for BRCA1/BRCA2 mutations, with the aim of detecting new genes contributing to breast and/or ovarian cancer predisposition." (PMID 22314128, 2012). "However none of the four basal-subtype ER-negative BRCA1-deficient breast carcinoma cell lines (HCC1937, MDA-MB-436, SUM149, and SUM1315) we studied expressed TBX2 protein at detectable levels or exhibited TBX2 gene amplification." (PMID 22844464, 2012). "Therefore, hereditary but not sporadic breast cancer seems to be characterized by short telomeres, primarily in BRCA1 and BRCA2 mutation carriers, but also in a subgroup of BRCAX." (PMID 21829373, 2011). "We used genotype data on up to 11,421 BRCA1 and 7,080 BRCA2 carriers, of whom 4,310 had been affected with breast cancer and had information on either ER or PR status of the tumour, to assess the associations of 12 loci with breast cancer tumour characteristics." (PMID 22053997, 2011). "This study suggests that using tamoxifen in BRCA1/2-mutation carriers who have not undergone a BSO may result in a decreased risk of breast cancer." (PMID 22312502, 2011). "Risk factors for the development of CNS metastases from breast cancer include patient characteristics, such as young age and African-American ethnicity, and biological features of the tumor, including ER-negativity, HER2-positivity, high tumor grade, and BRCA1 phenotype." (PMID 21929800, 2011). "This is the case for the c.68_69del and c.5266dup mutations in BRCA1 and c.5946del mutation in BRCA2 (until recently referred in the literature as 185delAG, 5382insC and 6174delT, respectively) which are found in 10-12% of Ashkenazi Jewish women diagnosed with breast cancer." (PMID 22185575, 2011). "Since we were unable to detect any of our novel fusions in our screening of additional BRCA1-mutated, BRCA2-mutated or BRCA1/2-unrelated breast cancers, they may represent non-recurrent passenger mutations." (PMID 22032724, 2011). "We aimed to assess whether CHEK2 was subject to DAE in lymphoblastoid cell lines (LCLs) from high-risk breast cancer patients for whom no mutation in BRCA1 or BRCA2 had been identified." (PMID 21569354, 2011). "Thus, further studies to elucidate transcription factor occupancy on the BRCA1 promoter, including proximal and distal regions, in breast cancer cells with distinct molecular signatures would be critical to understanding the complex regulation of BRCA1 expression during tumor progression." (PMID 21668996, 2011). "However, the role of gene fusions in BRCA1-related breast cancers is not well understood." (PMID 22032724, 2011).
breast cancer (continued). "Due to the increased risk of IBTR and the elevated risk of CBC in BRCA1/2 mutation carriers, risk-reducing strategies such as BSO or the use of tamoxifen, for those with ER-positive tumors, should be employed as they have been shown to reduce breast cancer recurrence." (PMID 22295226, 2011). "The CHEK2-Breast Cancer Consortium reported a frequency of 5.1% for the CHEK2*1100delC variant in familial breast cancer cases who tested negative for BRCA1 and BRCA2 (Breast cancer 2, early onset) mutations, as opposed to 1.1% of carriers in the control population." (PMID 21569354, 2011). "Moreover, ongoing GWAS in BRCA1 and BRCA2 mutation carriers may also identify further modifiers of breast cancer risk for mutation carriers." (PMID 22053997, 2011). "Further analysis has shown that allelic variation at FGFR2, TNRC9, 8q24, 2q35, and 5p12 is associated with physiological characteristics of breast tumors, such as ER status, and specific FGFR2, MAP3K1, and TNRC9 variants may interact with BRCA1 and BRCA2 mutations to increase breast cancer risk." (PMID 21037853, 2010). "Furthermore, given the fact that we examine copy number changes it might be worthwhile to analyze a highly genomically unstable tumor type, such as BRCA1/2-related breast cancer." (PMID 20052266, 2010). "BRCA1 mRNA is reduced in sporadic breast cancer cells despite the absence of mutations." (PMID 20209131, 2010). "Also, gains known to be important in human BRCA1-mutated breast cancer show no (e.g. 3q gain) or only partial (e.g. the 5q loss) overlap with the mouse gains and losses." (PMID 20735817, 2010). "Furthermore, BRCA1 carriers may be more likely to be found among women who have a high probability of hereditary breast cancer and who have a long term survival." (PMID 20219108, 2010). "In a subgroup analysis of the National Surgical Adjuvant Breast and Bowel Project (NSABP-P1) trial, Tamoxifen was found to reduce the incidence of breast cancer in healthy BRCA2 mutation carriers but not in BRCA1 carriers when started at the age 35 years or older." (PMID 20961453, 2010). "In a segregation analysis of families identified through breast cancer cases diagnosed before age 55, the residual familial clustering after accounting for BRCA1 and BRCA2 mutations could be explained by a large number of low penetrance genes with multiplicative effects on breast cancer risk." (PMID 21060860, 2010). "In order to address the issue of whether ER+ BRCA1 cancers are more akin to sporadic ER+ breast cancers than to ER- BRCA1 cancers, we performed a case-control analysis in which the pathologic features of these tumors were compared with those of a control group of ER+ sporadic breast cancers." (PMID 20149218, 2010). "Finally, if loss of BRCA1 function does exist in the majority of ER+ BRCA1 breast cancers, it is possible that ER+ and ER- BRCA1 cancers originate from different cells of origin (e.g. early progenitor cell vs stem cell) leading to different phenotypic expressions." (PMID 20149218, 2010). "Furthermore, in a prospective study of 139 women with BRCA1 or BRCA2 mutations, after a mean follow-up of 3 years, breast cancer developed in 8 of 63 women who had elected surveillance, but in none of the 76 BRCA mutations carriers who had undergone prophylactic surgery." (PMID 20961453, 2010).
breast cancer (continued). "Additionally, we evaluated whether chemotherapy could play a role in the prognosis of BRCA1 carriers, providing more benefit in this patient population than in patients with sporadic breast cancer." (PMID 20219108, 2010). "Although the patient group was already selected for BRCA1 testing by positive family history of breast cancer that might include also presence of breast cancer in the individual there is a trend towards higher breast cancer frequency and incidence rate in mutation carriers." (PMID 21034437, 2010). "In addition, 2 (3.3%) families in which the index patients had bilateral breast cancer diagnosed at ages 44 and 49 years with negative family history found to have mutation in BRCA1 gene." (PMID 20579331, 2010). "This study cannot resolve whether ER+ breast cancers without loss of wt allele that develop in BRCA1 carriers are equivalent to ER+ sporadic breast cancers that occur in non-carriers." (PMID 21080930, 2010). "In addition, the strong correlation between tumor size and nodal status described for sporadic breast cancer patients, was absent in BRCA1 mutation carriers." (PMID 20398395, 2010). "Sporadic breast cancer is not usually associated with other cancers such as ovarian or male breast cancer and unlike BRCA1-positive carcinomas, which exhibit specific histological characteristics, sporadic breast cancer cases comprise a vast array of phenotypes." (PMID 21037853, 2010). "It has been reported that ER+ breast cancers may be more common as BRCA1 carriers age." (PMID 20149218, 2010). "Importantly, none of the mouse mammary tumors showed the tandem duplication phenotype that we have observed in human BRCA1-mutated and triple-negative breast tumors (that is, tumors that do not express ERBB2, and estrogen and progesterone receptors)." (PMID 20942901, 2010). "It has, therefore, been suggested that ER+ BRCA1-associated breast cancers may actually be incidental or sporadic rather than caused by a complete loss of BRCA1 function." (PMID 21080930, 2010). "These patients carry mutations in either BRCA1 or BRCA2 genes, but there also are familial breast cancer patients who do not carry mutations in BRCA1/2 and presumably have mutations in another unknown gene or gene(s) (termed non-BRCA1/2 or BRCAX patients)." (PMID 19995430, 2009). "In summary, we have demonstrated that DZNep selectively inhibits BRCA1-deficient but not BRCA1-proficient mammary tumor cells, and that this effect is mainly due to the fact that BRCA1-deficient cells are dependent on EZH2, whereas BRCA1-proficient cells are not." (PMID 19709408, 2009). "However, we estimate the lifetime risk for breast cancer to be 40% compared to 21% in the Collaborative Group study.However, in these studies, BRCA1 and BRCA2 testing were not conducted and mutation carriers were not excluded." (PMID 19088722, 2009). "About one-third of the genetic variants in BRCA1 and 50% of those found in BRCA2 reported by the Breast Cancer Information Core are considered genetic variants of unknown clinical significance, also known as unclassified variants (UVs), because of the uncertainty about their cancer risks." (PMID 19200354, 2009). "However, for most families who exhibit the characteristics of hereditary transmission of breast cancer, a BRCA1 or BRCA2 mutation is not detected." (PMID 19088722, 2009).
breast cancer (continued). "Consequently, most patients with BRCA1-mutated breast cancer do not benefit from therapeutics that target ER- or ERBB2/HER2-expressing tumour cells." (PMID 19904273, 2009). "Whether cancer stem cells occur in BRCA1-associated breast cancer and contribute to therapeutic response is not known." (PMID 18241344, 2008). "Furthermore, consistent with previous observation in several breast cancer cell lines, the CRE site is important for BRCA1 expression in ovarian granulosa cells, as both point mutation (mCRE-Luc) and deletion of the CRE site (USCAAT-Luc) abolished luciferase activity." (PMID 19568323, 2008). "However, if the breast cancer results from other factors that cause downregulation of BRCA1 – for instance, in the case of sporadic basal-like breast cancer – small molecules that activate BRCA1 E3 activity could be successful." (PMID 19007432, 2008). "Mutational analysis by direct sequencing of the entire coding region of the BRCA1 and BRCA2 genes on 37 breast cancer patients aged 40 years and under, with no reported family history of breast and/or ovarian cancers, identified a total of 14 BRCA1 and 17 BRCA2 sequence variants." (PMID 18431501, 2008). "Unlike breast cancer, where patients with germline mutations in BRCA1 or BRCA2 have cancers that are distinct from sporadic breast cancers on the basis of morphology or gene profiling, ovarian cancers with germline BRCA1 or BRCA2 mutations are indistinguishable from their sporadic counterparts." (PMID 18208621, 2008). "Additionally, detection of changes in the expression levels of BRCA1 and its interacting proteins in primary human breast tumors may further illuminate their role in the development of breast cancer." (PMID 17511879, 2007). "Similarly, another recent study used breast cancer cell lines to show how BRCA1/IFN-γ pathways may regulate target genes involved in innate immune response, providing another possible mechanism for tumor intrinsic IR gene expression variability." (PMID 17683518, 2007). "As of today, no tests are routinely performed to identify the subgroup of women who do not belong to high-risk breast cancer families (eg BRCA1 families) but who would nevertheless benefit from breast cancer screening at an earlier age owing to an increased risk for early-onset breast cancer." (PMID 17311016, 2007). "However BRCA1 and BRCA2 may account for less than 40% of all familial breast cancer; multiple low penetrance breast cancer predisposition genes are likely to account for the rest." (PMID 17697367, 2007). "However, for approximately one half of strongly hereditary breast cancer families, no BRCA1/2 mutation has been identified and other genes are believed to be important." (PMID 18053174, 2007). "Prophylactic removal of the ovaries and fallopian tubes has proven its value as a risk-reducing strategy for ovarian cancer as well as breast cancer and should therefore be the cornerstone in the management of BRCA1/2 mutation carriers, as long as no other effective screening tool is available." (PMID 17426707, 2007).
breast cancer (continued). "However, no consistent pattern of mutation of the BRCA1 gene has ever been identified in sporadic breast cancer tumours." (PMID 17663789, 2007). "Furthermore, in our study we observed a protective effect of induced abortions on breast cancer risk in BRCA2 (but not in BRCA1 carriers) and the direction of the observed effect is opposite to that which we would expect from recall bias." (PMID 16563180, 2006). "Specifically, in a study comparing mammography among 34 BRCA1 or BRCA2 mutation carriers with breast cancer vs. disease-free controls, false-negative mammography correlated independently with BRCA1/2 mutation, the histological feature of prominent pushing margins, and high breast density." (PMID 16800895, 2006). "Hence there is a need for screening a larger number of samples to investigate the role of BRCA1/BRCA2 gene mutations in the high-risk group of familial as well as early onset cases, which forms the largest group of breast cancer patients in the Indian population." (PMID 17018160, 2006). "However, the relationships between induced or spontaneous abortions and breast cancer risk in BRCA1 or BRCA2 carriers have not been well studied." (PMID 16563180, 2006). "However, for breast cancer the existence of known mutations that significantly increase risk (particularly mutations in the BRCA1 and BRCA2 genes, which are relatively common) rules out this solution." (PMID 17029623, 2006). "For the real data set, we evaluated the role of two tagging-single nucleotide polymorphisms (tSNPs) in the DNA repair gene, NBS1, and their association with female breast cancer in 462 cases and 572 controls selected to be BRCA1/2 mutation negative from 139 high-risk Utah breast cancer families." (PMID 16620382, 2006). "In this study, we aimed to evaluate whether there are BACH1 genetic variants that contribute to breast cancer risk by screening the BACH1 gene for germ line alterations among 43 Finnish BRCA1/2 negative breast cancer families." (PMID 16430786, 2006). "Moreover, several agents that may contribute to breast cancer development (polycyclic aromatic hydrocarbons (e.g., benzo(a)pyrene) and alcohol) downregulate BRCA1 expression." (PMID 16434996, 2006). "Thus, copy number alterations and epigenetic silencing of the BRCA1 gene in sporadic breast cancer could serve as Knudson's 'hits', which has previously been proposed by Esteller and colleagues." (PMID 16846527, 2006). "For this purpose, the complete sequence of the 47 exons and flanking intronic sequences of the ATR gene were analyzed in DNA samples from individuals affected with breast cancer from non-related BRCA1- and BRCA2-negative high-risk French Canadian breast/ovarian families." (PMID 17010193, 2006). "The number of samples analysed is small, but three of four breast cancers showed BRCA1 hypermethylation, which might indicate that in breast cancer complicated by a t-AML, the frequency of BRCA1 hypermethylation is higher than the 11–31% reported in the literature." (PMID 17047656, 2006). "Whether the finding of ductal epithelial atypia provides additional prognostic information for women already identified as being at high risk of developing breast cancer by virtue of their BRCA1/2 genetic status is not known." (PMID 16457692, 2005). "However, in Sweden, BRCA1/2 mutation testing is not normally performed on women younger than 25 years of age, unless a family member has developed breast cancer prior to age 30 years." (PMID 15756256, 2005). "Lakhani and colleagues studied the pathology of 82 familial breast cancers not attributable to BRCA1 or BRCA2 mutations, and they found these non-BRCA1/2 cancers to be of lower grade, to show less pleomorphism and to have a lower mitotic count than sporadic cancers or BRCA mutation-positive cancers." (PMID 15642173, 2005).